SCD (stearoyl-CoA desaturase)
Diseases named in the same sentence as SCD in open-access papers (continued):
Sharing a sentence is not in itself a finding about the gene and the disease.
skin infection (2 papers, 2008 to 2023). An inflammatory process affecting the skin, caused by bacteria, viruses, parasites, or fungi. "Spontaneous skin infections with S. xylosus have also been described in mice lacking the stearoyl-CoA desaturase (SCD1) enzyme, which is required for generation of lipids involved in establishing a water-permeability barrier in the skin." (PMID 37533118, 2023).
soft tissue sarcoma (2 papers, 2016 to 2021). A malignant neoplasm arising from muscle tissue, adipose tissue, blood vessels, fibrous tissue, or other supportive tissues excluding the bones. "In addition, increased levels of SCD-1 are associated with a poor prognosis for patients with soft tissue sarcomas." (PMID 33289496, 2021).
teratoma (2 papers, 2020 to 2021). A non-seminomatous germ cell tumor characterized by the presence of various tissues which correspond to the different germinal layers (endoderm, mesoderm, and ectoderm). "For example, an inhibitor of stearoyl-CoA desaturase (SCD), PluriSIns #1, has been shown to prevent teratoma formation." (PMID 32493501, 2020). "In fact, the use of some small molecules, such as an inhibitor of stearoyl-CoA desaturase 1 (SCD1) or N-benzylnonanamide JC101, has been demonstrated to prevent teratoma formation." (PMID 33585434, 2021).
alcoholic liver diseases (1 paper, 2021). A disorder caused by damage to the liver parenchyma due to alcohol consumption. "SREBP1 plays a critical role in alcoholic liver disease, and it could regulate the transcription of downstream signaling, such as FASN, SCD, and ACLY." (PMID 34690775, 2021).
benign breast disease (1 paper, 2023). "This study compared the FA profiles, desaturase index (DI), and stearoyl CoA desaturase 1 (SCD1) mRNA levels in the AT that surrounds tumors in women with BC and benign breast disease (BBD)." (PMID 37885725, 2023).
cardiomyopathy (1 paper, 2023). A disease of the heart muscle or myocardium proper. "CD36 and SCD were mainly upregulated in some cardiomyopathy- and metabolism-related pathways and downregulated in some immune- and metabolism-related pathways." (PMID 37415143, 2023).
complement deficiency (1 paper, 2025). A genetic deficiency of any of the component of the complement system (including the classical, alternative, and terminal pathway components), that can either be acquired or inherited. "The lung cross-species signature includes multiple carcinoma-associated genes (TNR, SCD) and, to a lesser extent, genes involved in complement deficiency (CFD, C3) and NAD+ metabolism (NNMT), all of which may be considered aging-associated processes." (PMID 40249926, 2025).
Crohn disease (1 paper, 2025). A gastrointestinal disorder characterized by chronic inflammation involving all layers of the intestinal wall, noncaseating granulomas affecting the intestinal wall and regional lymph nodes, and transmural fibrosis. "This study delineates the role of ferroptosis in Crohn’s disease by identifying seven hub ferroptosis-related differentially expressed genes, notably SCD, which are closely linked to immune dysregulation." (PMID 41515900, 2025). "The translational potential of targeting SCD is further supported by its conserved dysregulation in human disease, offering a novel strategy for immunomodulatory intervention in Crohn’s disease and potentially other ferroptosis-associated inflammatory disorders." (PMID 41515900, 2025). "By integrating multi-omics approaches, this study reveals a crucial connection between ferroptosis and immune microenvironment dysregulation in Crohn’s disease (CD), identifying seven hub ferroptosis-related differentially expressed genes (FEDGs): SCD, ATF4, SAT1, RPL8, MUC1, MTDH, and ATP6V1G2." (PMID 41515900, 2025). "In summary, our study significantly advances the understanding of Crohn’s disease pathogenesis by systematically integrating multi-omics data with functional validation to delineate the role of ferroptosis-related genes, particularly SCD, in modulating intestinal immunity and inflammation." (PMID 41515900, 2025).
diabetic foot ulceration (1 paper, 2023). "Besides, NFKBIA affects the wound healing in diabetic foot ulceration (DFU) (p=0.006), MYC and SCD are related to pyroptosis and immune infiltration in T2DM (p=0.001)." (PMID 37293508, 2023).
Ewing sarcoma (1 paper, 2020). A small round cell tumor that lacks morphologic, immunohistochemical, and electron microscopic evidence of neuroectodermal differentiation. "In addition, silencing of either FASN, SCD or SPTLC1 markedly reduced cell proliferation of Ewing sarcoma, further corroborating this conclusion." (PMID 33080033, 2020).
Follicular Cyst (1 paper, 2023). Cyst due to the occlusion of the duct of a follicle or small gland. "FGF7 regulated the PPAR signaling pathway (FABP5 and SCD) and the MAPK signaling pathway (FGF1, FGFR2, IL1A, TGFB1, and CSF1) and pathways in cancer (IL7, CD44, SMAD2, and MMP2) may be involved in the formation of follicular cysts." (PMID 38274662, 2023).
fungal infection (1 paper, 2014). "An oral dose of 100 mg/kg bw of SCD-1 did not result in significant (p<0.05) reduction in the level of serum biochemical parameters post fungal infection." (PMID 25140804, 2014).
G6PD deficiency (1 paper, 2020). An X-linked genetic condition caused by alterations in the gene G6PD that result in moderately to severely decreased activity levels of the enzyme glucose-6-phosphate dehydrogenase. "Moreover, it is the only one addressing the relationships between oxidative stress, clinical severity, and so many genetic polymorphisms since we tested both the three common SCD genetic modifiers (alpha-thal, G6PD deficiency, and HbF) and common oxidative stress polymorphisms in different genes." (PMID 32937882, 2020).
hyperphosphatemia (1 paper, 2020). Abnormally high level of phosphate in the blood. "Together, these results suggest that hyperphosphatemia in CKD rats may be involved in the reduction of the SCD mRNA expression and its activity in GM." (PMID 33041516, 2020).
Hypoxemia (1 paper, 2018). An abnormally low level of blood oxygen. "Hypoxemia may disturb lipid metabolism by upregulating hepatic SCD-1, leading to de novo TG synthesis, an increase of adipose tissue lipolysis, lipoprotein secretion and decrease of lipoprotein clearance." (PMID 29623044, 2018).
Impaired glucose tolerance (1 paper, 2009). An abnormal resistance to glucose, i.e., a reduction in the ability to maintain glucose levels in the blood stream within normal limits following oral or intravenous administration of glucose. "In the same study treatment with the PPARγ agonist pioglitazone increased the SCD expression and insulin sensitivity in subjects with impaired glucose tolerance." (PMID 19689798, 2009).
intracranial hemorrhage (1 paper, 2021). Bleeding within the SKULL, including hemorrhages in the brain and the three membranes of MENINGES. "Unexpectedly, in addition to reducing tumor burden, the SCD inhibitor blocked intracranial hemorrhage, suggesting a secondary effect on tumor vasculature." (PMID 33568479, 2021).
lipidosis (1 paper, 2022). "In addition, we first reported that ssc-miR-133a-3p, ssc-miR-486 and ssc-miR-1 regulate the target genes CPT1A, SCD5 and SCD, respectively, in the PPAR signaling pathway so that they can have an impact on lipidosis." (PMID 36672834, 2022).
nasopharyngeal carcinoma (1 paper, 2022). A carcinoma arising from the nasopharyngeal epithelium. "In nasopharyngeal carcinoma (NPC), HIF-1α upregulates the expression of stearoyl-CoA desaturase 1 (SCD1), which mediates the production of monounsaturated fatty acids and inhibits ferroptosis." (PMID 35624785, 2022).
Nephropathy (1 paper, 2019). A nonspecific term referring to disease or damage of the kidneys. "Our study also showed that SCD-1 and Elovl-6 expressions were increased in the liver of the CsA-induced nephropathy rat model and their enzyme expressions and oleic acid contents were decreased after omega-3 FA supplementation." (PMID 30943799, 2019). "In our study, renal SREBP-1, LXR, and SCD-1 expression levels increased, but Elovl-6 expression was decreased in the CsA-induced nephropathy rat model." (PMID 30943799, 2019). "Omega-3 FA supplementation decreased the erythrocyte membrane oleic acid content by modulating SCD-1 and Elovl-6 expression in the kidney and liver of CsA induced nephropathy rats." (PMID 30943799, 2019). "Therefore, increased erythrocyte membrane oleic acid contents and higher SCD‐1 expressions of kidney and liver in a CsA-induced nephropathy rat model reflect that CsA-induced nephropathy induces metabolic disorder like feeding high-carbohydrate diet." (PMID 30943799, 2019). "In addition, SCD-1 expression increased in both the kidney and liver of the CsA-induced nephropathy rat model, which was found to be reversed by omega-3 FA supplementation." (PMID 30943799, 2019).
peripheral nerve injury (1 paper, 2014). Injury to a peripheral nerve. "We recently described that knock-out mice for SCD-1, and non-transgenic mice treated with a SCD-1 inhibitor, present improved nerve regeneration after peripheral nerve injury." (PMID 24600344, 2014).
phospholipidosis (1 paper, 2012). "However, it is clear that our model predicts that the induction of phospholipidosis via the mechanism 3 targets ELOVL6 or SCD is unlikely, as neither is predicted to interact with any of the 100 positive phospholipidosis-inducing compounds." (PMID 22281160, 2012).
postmenopausal osteoporosis (1 paper, 2023). Metabolic disorder associated with fractures of the femoral neck, vertebrae, and distal forearm. "SCD1, stearoyl CoA desaturase 1, was found to promote the function of osteogenesis in bone marrow mesenchymal stem cells, and inhibition of SCD1 could prevent postmenopausal osteoporosis to some extent." (PMID 37008941, 2023).
skin tumors (1 paper, 2019). "SCD expression strongly correlates with principal component 1 (PC1) towards skin tumors." (PMID 31316083, 2019).
Stroke (1 paper, 2025). Sudden impairment of blood flow to a part of the brain due to occlusion or rupture of an artery to the brain. "Stearoyl-CoA-desaturase (SCD)-16 (i.e. ratio of 16:1 to 16:0) was also positively associated with stroke risk even after maximal adjustments." (PMID 39365172, 2025).
synovial sarcoma (1 paper, 2019). "For group 2 (MPNST and SS) genes related to neural differentiation such as NEURL1 and NPAS1 were identified, which were found to be upregulated in synovial sarcomas, while SCD, an enzyme involved in fatty acid biosynthesis, is more highly expressed in MPNST." (PMID 30785874, 2019).
ventricular dilatation (1 paper, 2023). "In contrast, the inverse correlation of single double bonds of fatty acids with MetS score, BMI, and almost all atrial and ventricular dilatation markers may indicate a lower degree of SCD-1 activity." (PMID 37085694, 2023).
vitamin D deficiency (1 paper, 2020). A nutritional condition produced by a deficiency of VITAMIN D in the diet, insufficient production of vitamin D in the skin, inadequate absorption of vitamin D from the diet, or abnormal conversion of vitamin D to its bioactive metabolites. "A recent ground-breaking study reported that vitamin D deficiency downregulated SCD activity in the rat." (PMID 32528735, 2020). "Noting that vitamin D deficiency decreases SCD in the periphery, we propose it also decreases SCD in oligodendrocytes, disrupting the nervonic acid supply and causing myelin instability and fragmentation." (PMID 32528735, 2020). "Finally, very new data show that vitamin D deficiency depressed SCD activity in rat peripheral tissues." (PMID 32528735, 2020).
cancer (491 papers, 2006 to 2026). A tumor composed of atypical neoplastic, often pleomorphic cells that invade other tissues. "SCD activity has been implicated in cancer cell survival, and its overexpression has been identified in several malignancies, often in association with adverse prognosis." (PMID 40404984, 2025). "SCD inhibitors are particularly effective in blocking cancer cell proliferation, as their effects are linked to AMPK activation, which phosphorylates ACC and inhibits FA synthesis." (PMID 41306968, 2025). "OA, a monounsaturated fatty acid, has been shown to influence cancer cell stemness and survival under glucose-deficient conditions by activating stearoyl-CoA desaturase (SCD), which in turn promotes YAP nuclear translocation." (PMID 41227346, 2025). "SCD upregulation was previously associated with the metabolic reprogramming necessary to promote metastasis of CRC cancer cells." (PMID 38200223, 2024). "Lipid metabolic reprogramming is considered a hallmark of cancer, and the role of SCD reveals the potential of targeting ferroptosis, a regulated cell death process, as a therapeutic strategy." (PMID 39107713, 2024). "Particularly blocking SCD activity, is of potential translational interest to promote ferroptosis susceptibility for cancer therapy." (PMID 39009641, 2024). "Fatty acid synthesis enzymes, including ACC, FASN, and SCD, are upregulated in various cancers and are associated with cancer progression." (PMID 38610991, 2024). "Based on multivariate analysis, SCD or FADS2 was identified as a prognostic risk factor for 33 types of cancer, especially BRCA." (PMID 38905386, 2024). "Increased SCD activity, which led to the synthesis of more monounsaturated fatty acids, was associated with potentially promoting cancer cell growth and infiltration." (PMID 39104534, 2024). "Here, we elucidated that role of stearoyl-CoA desaturase (SCD) increased by treatment with cancer-associated fibroblast (CAF) supernatant in CD4+ T cells on their subset differentiation and activity of CD8+ T cells." (PMID 39543650, 2024). "The University of Alabama at Birmingham cancer data analysis portal database indicates that the expression and methylation levels of SCD or FADS2 are associated with various clinicopathological factors in patients with BRCA." (PMID 38905386, 2024). "More importantly, SCD has also been linked to chemoresistance in certain types of cancers, including HCC." (PMID 36472914, 2023). "For instance, the fatty acid desaturase 2 (FADS2) pathway, an alternative FA desaturation pathway bypassing stearoyl-CoA desaturase 1 (SCD1), can cause an abnormal and elevated amount of n-10 isomers, adding to cancer plasticity." (PMID 36951803, 2023). "SCD is ubiquitously expressed in most cancer cells, and its levels are tightly associated with the aggressiveness of cancers." (PMID 36472914, 2023). "Previous research demonstrated that SCD is a biochemical hallmark of cancer cells and that it modulates fatty acid composition in cancer." (PMID 38003694, 2023). "A Swedish men study also showed an association between single-nucleotide polymorphisms in the SCD-1 gene and cancer death." (PMID 37373069, 2023). "By OA treatment under glucose deficient condition, cancer cell stemness was significantly enhanced through sequential activation of SCD, F-actin polymerization and nuclear translocation of yes-associated protein." (PMID 36514170, 2022). "Our data indicated that activation of the lipid metabolism by SCD is critical for the maintenance of stemness of cancer cells under glucose deficient condition." (PMID 36514170, 2022). "Transferred CAF-derived OA through lipid transporter upregulated SCD in cancer cells under glucose-deficient conditions, resulting in enhanced lipid metabolism and autophagosome maturation." (PMID 36514170, 2022).
cancer (continued). "High SCD activity and alteration in the balance between saturated and monounsaturated fatty acids are implicated in various diseases, including cancer, diabetes, atherosclerosis, and obesity." (PMID 36140684, 2022). "SCD is the enzyme that converts saturated fatty acids to Δ9-monounsaturated fatty acids, implicated in a variety of cancers." (PMID 35370706, 2022). "SCD activity and association with cancer risk factors in humans varies by cancer type and SCD isoform." (PMID 36581893, 2022). "SCD overexpression, or up-regulated activity, has been associated with tumor aggressiveness and poor prognosis in many cancer types." (PMID 34503180, 2021). "Our data demonstrate inhibitor-induced SCD overexpression in cancer cells causes massive reprograming of the lipogenic pathway during acquisition of resistance to SCD inhibitors." (PMID 33568479, 2021). "The expression and activity of SCD are upregulated in several cancers and are significantly associated with tumor progression and patient outcome." (PMID 35006438, 2021). "Previous research has implicated these enzyme systems in cancer, with overexpression of SCD-1 being linked to progression and growth of hepatocellular, renal, colorectal and prostate cancers." (PMID 34421820, 2021). "In the ovarian cancer cell population, the activity of stearoyl-CoA desaturase 1 (SCD1), an enzyme involved in monounsaturated FA synthesis, was strongly associated with LD levels and cancer stemness." (PMID 32029741, 2020). "The role of PL maintenance and composition in disease is not fully understood; however, it certainly warrants further study particularly as SCD is an active drug target, and its dysregulation has been directly implicated in the onset of cancer." (PMID 26528916, 2015). "Recently, it has been shown that cancer survival is dependent on unsaturated fatty acids and is implicated SCD in this process." (PMID 25243088, 2014). "Both normal and cancer cells were treated with the SCD inhibitor in serum-deficient media and the effect of the SCD inhibitor on cell growth was independent of the presence of serum (data not shown)." (PMID 20613975, 2010). "Recently, stearoyl CoA desaturase 1 (SCD1), an enzyme that catalyzes the rate-limiting step in monounsaturated fatty-acid synthesis, has been associated with ferroptosis resistance in a number of cancers and correlated with a worse prognosis." (PMID 37132605, 2024). "Additionally, hypoxia triggers the release of monounsaturated fatty acids (MUFAs) from lipid droplets to compensate for loss of SCD activity in cancer cells." (PMID 39284708, 2024). "Furthermore, we revealed that autophagosome synthesis regulated the SCD expression in cancer cells under the glucose deficient condition." (PMID 36514170, 2022). "Thus, heightened SCD activity is advantageous to cancer cells, as it results in fewer peroxidation-susceptible targets." (PMID 34983949, 2022). "However, inhibition of fatty acid desaturation following ablation of SCD causes oxidative stress, cell cycle inhibition, and apoptosis in cancer cells." (PMID 29359123, 2017). "SREBPs mediate the activation of multiple genes by binding to sterol regulatory elements within the regulatory regions of genes such as FASN, which encodes fatty acid synthase (FASN), and SCD, which encodes stearoyl CoA desaturase-1 (SCD-1) and is involved in LD formation in cancer cells." (PMID 27589734, 2016). "Furthermore, genes encoding lipogenic enzymes such as FASN and SCD-1 are upregulated in cancer cells in response to hypoxia." (PMID 27589734, 2016).